OR56A4 (olfactory receptor family 56 subfamily A member 4)
Description:
Odorant receptor.
Synonyms: OR11-49
Tractability: Antibody: its Gene Ontology location is reachable by antibodies, with high confidence; UniProt places it where antibodies can reach, with medium confidence; UniProt predicts a signal peptide or a membrane-spanning region.
Gene: Protein-coding gene on chromosome 11 (5,999,445 to 6,006,946, reverse strand). Ensembl gene ENSG00000183389.
Subcellular location: Cell membrane
Pathways (Reactome):
Sensory Perception: Expression and translocation of olfactory receptors; Olfactory Signaling Pathway
Gene Ontology:
Molecular function: olfactory receptor activity; G protein-coupled receptor activity; signaling receptor activity
Biological process: cellular response to lipid; detection of chemical stimulus involved in sensory perception of smell; G protein-coupled receptor signaling pathway; system process
Cellular component: plasma membrane; membrane
Genetic constraint (gnomAD): Loss-of-function variants: 9 observed, 14.13 expected, observed/expected ratio (o/e) 0.64, 90% interval 0.38 to 1.11. The upper end of that interval is the gene's LOEUF score, 1.11, which puts it in group 4 of 6, group 1 being the genes least tolerant of losing a copy. Missense variants: 380 observed, 388.34 expected, observed/expected ratio (o/e) 0.98, 90% interval 0.9 to 1.07. Synonymous variants: 167 observed, 158.14 expected, observed/expected ratio (o/e) 1.06, 90% interval 0.93 to 1.2.
Homologues: Orthologues: chimpanzee OR56A4 (99% identical), dog OR56A4 (90% identical), rabbit OR56A4 (90% identical), rat Or56a3b (87% identical), mouse Or56a4 (87% identical), mouse Or56a5 (83% identical), rat Olr193 (83% identical), zebrafish adra1ab (19% identical), Caenorhabditis elegans ser-5 (16% identical), zebrafish adra2da (16% identical), zebrafish adra2db (15% identical). Paralogues in human: OR56A5 (87% identical), OR56A1 (83% identical), OR56A3 (76% identical), OR13F1 (32% identical), OR5T1 (30% identical), OR5T3 (29% identical), OR5T2 (27% identical), ADRB1 (19% identical), ADRA1A (18% identical), ADRA1B (18% identical), ADRB3 (18% identical), DRD2 (17% identical), and 6 more.
Diseases named in the same sentence as OR56A4 in open-access papers:
OR56A4 is named in the same sentence as 2 diseases in open-access papers, as found by Europe PMC text mining. Sharing a sentence is not in itself a finding about the gene and the disease.
OR56A4 shares sentences with these, for which no sentence is quoted: hypothyroidism (1 paper); pancreatic tumors (1).